LINC01093 (long independently transcribed non-coding RNA 1093)
Gene: Long non-coding RNA gene on chromosome 4 (184,892,858 to 184,899,908, reverse strand). Ensembl gene ENSG00000249173.
Diseases named in the same sentence as LINC01093 in open-access papers:
LINC01093 is named in the same sentence as 6 diseases in open-access papers, as found by Europe PMC text mining. Sharing a sentence is not in itself a finding about the gene and the disease. The quoted sentences say what the papers report.
Cirrhosis (1 paper, 2018). A chronic disorder of the liver in which liver tissue becomes scarred and is partially replaced by regenerative nodules and fibrotic tissue resulting in loss of liver function. "Unexpectedly, LINC01093 expression was higher in cirrhosis of recurrent patients." (PMID 30416681, 2018).
hepatocellular adenoma (1 paper, 2025). A benign epithelial neoplasm arising from the hepatocytes. "Another study demonstrated downregulation of LINC01093 expression in HBL, non‐malignant hepatocellular adenoma and focal nodular hyperplasia in comparison to adjacent liver tissues, whereas CCA samples were characterized by total lack of LINC01093." (PMID 40596757, 2025).
hepatocellular carcinoma (1 paper, 2022). A malignant tumor that arises from hepatocytes. "Linc01093 triggered the mRNA decay of GLI1 through interaction with IGF2BP1 to suppress hepatocellular carcinoma (HCC progression." (PMID 36221055, 2022).
liver cancer (1 paper, 2025). An epithelial or non-epithelial malignant neoplasm that arises from the liver. "Thus, LINC01093 might be considered as potential therapeutic target for HBV‐associated liver cancer." (PMID 40596757, 2025). "Its application as liver cancer biomarker is discussible, as decreased LINC01093 expression is shown also in ALD, however among other types of tumors LINC01093 seems to be detected mainly in HCC." (PMID 40596757, 2025).
tumor (2 papers, 2019 to 2021). "In the lncRNA group, lncRNA-TOB2P1, LOC100499489, lnc-NMRAL2p, and lnc-NBPF22P were markedly upregulated in tumor tissues, while LINC01093, LOC100130899, LOC200772, and lnc-FENDRR were significantly downregulated in tumor tissues, compared to the adjacent controls." (PMID 31156698, 2019). "LINC01093 has been shown to be significantly downregulated in HCC and was correlated with tumor cell proliferation and metastasis." (PMID 34257652, 2021).
LINC01093 also shares sentences with these, for which no sentence is quoted: liver fibrosis (1 paper).